SEH1L (SEH1 like nucleoporin)
Description:
Component of the Nup107-160 subcomplex of the nuclear pore complex (NPC). The Nup107-160 subcomplex is required for the assembly of a functional NPC. The Nup107-160 subcomplex is also required for normal kinetochore microtubule attachment, mitotic progression and chromosome segregation. This subunit plays a role in recruitment of the Nup107-160 subcomplex to the kinetochore. As a component of the GATOR2 complex, functions as an activator of the amino acid-sensing branch of the mTORC1 signaling pathway. The GATOR2 complex indirectly activates mTORC1 through the inhibition of the GATOR1 subcomplex. GATOR2 probably acts as an E3 ubiquitin-protein ligase toward GATOR1. In the presence of abundant amino acids, the GATOR2 complex mediates ubiquitination of the NPRL2 core component of the GATOR1 complex, leading to GATOR1 inactivation. In the absence of amino acids, GATOR2 is inhibited, activating the GATOR1 complex. Within the GATOR2 complex, SEC13 and SEH1L are required to stabilize the complex.
Synonyms: SEC13L; SEH1; SEH1A; SEH1B
Tractability: PROTAC: UniProt records ubiquitination sites on it; ubiquitination databases record sites on it; its protein half-life has been measured.
Gene: Protein-coding gene on chromosome 18 (12,947,133 to 12,987,667, forward strand). Ensembl gene ENSG00000085415.
Subcellular location: Chromosome, centromere, kinetochore; Nucleus, nuclear pore complex; Lysosome membrane
Pathways (Reactome):
Disease: Defective TPR may confer susceptibility towards thyroid papillary carcinoma (TPC); HCMV Early Events; HCMV Late Events; NEP/NS2 Interacts with the Cellular Export Machinery; NS1 Mediated Effects on Host Pathways; Nuclear import of Rev protein; Rev-mediated nuclear export of HIV RNA; SARS-CoV-2 activates/modulates innate and adaptive immune responses; Transport of Ribonucleoproteins into the Host Nucleus; Viral Messenger RNA Synthesis; Vpr-mediated nuclear import of PICs
Cell Cycle: Amplification of signal from unattached kinetochores via a MAD2 inhibitory signal; EML4 and NUDC in mitotic spindle formation; Mitotic Prometaphase; Nuclear Pore Complex (NPC) Disassembly; Postmitotic nuclear pore complex (NPC) reformation; Resolution of Sister Chromatid Cohesion; Separation of Sister Chromatids
Metabolism of RNA: Transport of Mature mRNA Derived from an Intronless Transcript; Transport of Mature mRNA derived from an Intron-Containing Transcript; Transport of the SLBP Dependant Mature mRNA; Transport of the SLBP independent Mature mRNA; snRNP Assembly; tRNA processing in the nucleus
Metabolism of proteins: SUMOylation of DNA damage response and repair proteins; SUMOylation of DNA replication proteins; SUMOylation of RNA binding proteins; SUMOylation of SUMOylation proteins; SUMOylation of chromatin organization proteins; SUMOylation of ubiquitinylation proteins
Metabolism: IP3 and IP4 transport between cytosol and nucleus; IP6 and IP7 transport between cytosol and nucleus; IPs transport between nucleus and cytosol; Regulation of Glucokinase by Glucokinase Regulatory Protein
Cellular responses to stimuli: Amino acids regulate mTORC1; Regulation of HSF1-mediated heat shock response
Immune System: ISG15 antiviral mechanism
Signal Transduction: RHO GTPases Activate Formins
Gene Ontology:
Molecular function: protein binding; structural molecule activity
Biological process: attachment of mitotic spindle microtubules to kinetochore; cellular response to amino acid starvation; cellular response to nutrient levels; mitotic metaphase chromosome alignment; nuclear pore organization; positive regulation of TORC1 signaling; protein-containing complex localization; negative regulation of TORC1 signaling; nucleocytoplasmic transport
Cellular component: GATOR2 complex; kinetochore; lysosomal membrane; nuclear envelope; nuclear pore outer ring; cytosol; nuclear pore; Seh1-associated complex
Genetic constraint (gnomAD): Loss-of-function variants: 16 observed, 38.62 expected, observed/expected ratio (o/e) 0.41, 90% interval 0.28 to 0.63. The upper end of that interval is the gene's LOEUF score, 0.63, which puts it in group 2 of 6, group 1 being the genes least tolerant of losing a copy. Missense variants: 365 observed, 497.34 expected, observed/expected ratio (o/e) 0.73, 90% interval 0.67 to 0.8. Synonymous variants: 155 observed, 174.49 expected, observed/expected ratio (o/e) 0.89, 90% interval 0.78 to 1.01.
Homologues: Orthologues: rabbit SEH1L (97% identical), guinea pig SEH1L (95% identical), rat Seh1l (95% identical), pig SEH1L (94% identical), tropical clawed frog seh1l (86% identical), chimpanzee SEH1L (85% identical), mouse Seh1l (82% identical), zebrafish seh1l (71% identical), Drosophila melanogaster Nup44A (47% identical), Caenorhabditis elegans npp-18 (32% identical). Paralogues in human: SEC13 (25% identical).
Diseases named in the same sentence as SEH1L in open-access papers:
SEH1L is named in the same sentence as 30 diseases in open-access papers, as found by Europe PMC text mining. Sharing a sentence is not in itself a finding about the gene and the disease. The quoted sentences say what the papers report.
breast carcinoma (4 papers, 2023 to 2025). "SEH1L has emerged as a promising therapeutic target in various malignancies and other pathological conditions, and it plays a significant role in regulating the mechanistic target of rapamycin (mTOR) pathway in breast cancer." (PMID 40781725, 2025). "Although functional studies have not directly implicated MAP2K1, POLR2J, and SEH1L in breast cancer development and progression, they have been associated with other malignancies." (PMID 38418940, 2024). "Despite this discrepancy, SEH1L, similar to ZYX, GJA1, and TUBA4A, was upregulated in DOX-resistant breast cancer cells in the independent transcriptomic dataset GSE76540." (PMID 41153808, 2025). "SSBP1, TXNRD1, SLC25A5, DDOST, SEH1L, and MCM2 had a significant effect in at least 50% of breast cancer cell lines in the CRISPR-Cas9 and/or RNAi screening data." (PMID 37445737, 2023).
hepatocellular carcinoma (4 papers, 2024 to 2025). A malignant tumor that arises from hepatocytes. "SEH1L promotes hepatocellular carcinoma progression by inhibiting ferroptosis, while its silencing induces ferroptosis via the ATF3/HMOX1/GPX4 axis, suppressing tumor growth." (PMID 39315094, 2024). "The researchers additionally observed that SEH1L was significantly upregulated in hepatocellular carcinoma (HCC)." (PMID 40034747, 2025). "This study indicated that SEH1L siliencing could induce ferroptosis and suppresses hepatocellular carcinoma (HCC) progression via ATF3/HMOX1/GPX4 axis." (PMID 39095556, 2024).
melanoma (2 papers, 2020 to 2024). A malignant, usually aggressive tumor composed of atypical, neoplastic melanocytes. "It was reported that HIPK2 was the tumor suppressor, while SEH1L was correlated with the time of disease-free status in melanoma." (PMID 32640634, 2020).
adrenocortical carcinoma (1 paper, 2024). "High expression of SEH1L was associated with poor OS in adrenocortical carcinoma (ACC), KICH, brain lower grade glioma (LGG), LIHC, mesothelioma (MESO), pancreatic adenocarcinoma (PAAD), prostate adenocarcinoma (PRAD) and sarcomav (SARC)." (PMID 39095556, 2024).
cholangiocarcinoma (1 paper, 2024). A carcinoma that arises from the intrahepatic biliary tree (intrahepatic cholangiocarcinoma) or from the junction, or adjacent to the junction, of the right and left hepatic ducts (hilar cholangiocarcinoma). "The results suggested that SEH1L was significantly up-regulated in most human cancers, including breast invasive cancer (BRCA), cholangiocarcinoma (CHOL), colon adenocarcinoma (COAD) and so on." (PMID 39095556, 2024).
epilepsy (1 paper, 2025). A brain disorder characterized by episodes of abnormally increased neuronal discharge resulting in transient episodes of sensory or motor neurological dysfunction, or psychic dysfunction. "Additionally, SEH1L is strongly associated with macrophage function and has been implicated in the pathophysiology of epilepsy and other neurodevelopmental disorders." (PMID 40781725, 2025).
esophageal carcinoma (1 paper, 2024). A primary or metastatic malignant neoplasm involving the esophagus. "SEH1L can serve as a potential diagnostic biomarker in COAD, esophageal carcinoma (ESCA), KICH, LIHC, lung squamous cell carcinoma (LUSC) and stomach adenocarcinoma (STAD) (AUC: 0.861, 0.803, 0.839, 0.753, 0.826 and 0.932 respectively)." (PMID 39095556, 2024).
Obesity (1 paper, 2020). Accumulation of substantial excess body fat. "From the GWAS, the significant markers associated with obesity-related traits including body weight (CACNA1B, C22orf39, U6, MYH14, PTPN2, SEH1L) and blood sugar (PRSS55, GRIK2), were identified." (PMID 33182249, 2020).
ovarian tumor (1 paper, 2021). "The expression levels of ANGPTL4, PYGB and IRS2 were upregulated and those of ISG20 and SEH1L were downregulated in ovarian tumor tissues compared with normal tissues." (PMID 34229669, 2021).
sarcoma (1 paper, 2023). A usually aggressive malignant neoplasm of the soft tissue or bone. "Multiple genes were downregulated (p < 0.05) in sarcoma tumors, including HSP90AB1, IGHA1, INSM1, IRF5, MAP2K2, and SEH1L." (PMID 37445737, 2023).
transitional cell carcinoma (1 paper, 2020). A malignant neoplasm arising from the transitional epithelium, usually affecting the urinary bladder, ureter, or renal pelvis. "In the transitional cell carcinoma lymphatic metastasis, we identified HIPK2 and SEH1 like nucleoporin (SEH1L)." (PMID 32640634, 2020).
uterine corpus endometrial carcinoma (1 paper, 2024). A endometrial carcinoma (disease) that involves the body of uterus. "High SEH1L expression was a risk factor for shorter progression free interval (PFI) in ACC, KICH, LIHC, PAAD, uterine corpus endometrial carcinoma (UCEC) and uveal melanoma (UVM)." (PMID 39095556, 2024).
tumor (6 papers, 2021 to 2025). "Surprisingly, the overexpression of SEH1L and TCF3 was associated with vice versa high sensitivity of tumor cells to these compounds." (PMID 41153808, 2025). "The relationship between miR-21, miR-17, and miR-155 and the novel MDR markers such as SEH1L, TUBA4A, and ZYX was revealed, thereby expanding the current understanding of the molecular mechanisms underlying tumor cell resistance to chemotherapy." (PMID 41463125, 2025). "We applied immunohistochemistry, western blotting and qRT-PCR to detect the differences in the expression of ISG20 and SEH1L between paired tumor tissues and adjacent non-tumor tissues." (PMID 34229669, 2021). "Consistent with the database results, our experiments confirmed that ISG20 and SEH1L are expressed at low levels in tumor tissues and that both of these genes can inhibit the proliferation, invasion, and migration of OS cells." (PMID 34229669, 2021). "Stable overexpression of ISG20 or SEH1L by pLVX-ISG20-IRES-Neo or pLVX-SEH1L-IRES-Neo in Caov3 cells reduced tumor growth." (PMID 34229669, 2021). "The tumor of the SEH1L knock down group grew slower than that of the control group." (PMID 39095556, 2024). "The expression levels of ISG20 and SEH1L were lower in tumor tissues than in normal tissues." (PMID 34229669, 2021). "Finally, the expression and function of the unreported signature genes ISG20 and SEH1L were explored using immunohistochemistry, western blotting, qRT-PCR, proliferation, migration, invasion and xenograft tumor assays." (PMID 34229669, 2021). "However, the interrelation between SEH1L expression and tumor progression is less studied." (PMID 39095556, 2024). "To address this issue, we calculated hazard ratio (HR) values for SEH1L, TUBA4A, TCF3, ZYX, and GJA1, both individually and in combination, using tumor data from The Cancer Genome Atlas (TCGA)." (PMID 41153808, 2025). "Considering these results, we speculated that the activation of SEH1L and TCF3 observed in DOX-resistant tumor cells may be a consequence of compensatory mechanisms in response to xenobiotic stress." (PMID 41153808, 2025). "Interestingly, three members of the GATOR2 complex (WDR59, MIOS, SEH1L) were found in our negative hits, underscoring the importance of these characterized GATOR2 components in promoting tumor growth in TNBC." (PMID 34031411, 2021).
cancer (4 papers, 2021 to 2025). A tumor composed of atypical neoplastic, often pleomorphic cells that invade other tissues. "In above section, we made a comprehensive analysis about the expression level, diagnostic value, prognostic value, mutation and methylation characteristic of SEH1L in pan-cancer." (PMID 39095556, 2024). "Next, we analyzed the correlation between SEH1L mutation and cancer prognosis." (PMID 39095556, 2024). "SEH1L is up-regulated and is associated with poor prognosis in pan-cancer." (PMID 39095556, 2024). "The mutation characteristics of SEH1L in pan-cancer was analyzed using cBioPortal database." (PMID 39095556, 2024). "Next, we assessed the diagnostic value of SEH1L in pan-cancer using ROC curve." (PMID 39095556, 2024). "The limited prior association of SEH1L, TUBA4A, ZYX, and TCF3 with chemoresistance, combined with their consistent dysregulation across cancer types, nominates them as novel and promising biomarker candidates for predicting DOX sensitivity." (PMID 41153808, 2025). "Based on previous work, we further analyzed the expression and potential function of SEH1L in pan-cancer." (PMID 39095556, 2024). "Interestingly, we found that SEH1L and TCF3 activation was associated with increased chemosensitivity to DOX in vitro in the Cancer Therapeutics Response Portal database, contrasting with our clinical findings." (PMID 41153808, 2025). "In our study, we made a comprehensive analysis about SEH1L, and found that it was significantly up-regulated in pan-cancer and may function as a biomarker." (PMID 39095556, 2024). "Then, the expression of SEH1L in pan-cancer was analyzed using Timer 2.0 database." (PMID 39095556, 2024). "Our results suggested that SEH1L was significantly up-regulated and related to poor prognosis in most cancers, and may serve as a potential biomarker." (PMID 39095556, 2024). "Based on the TCGA database, we further analyzed the prognostic value of SEH1L in pan-cancer." (PMID 39095556, 2024). "Our study showed that the expression of SEH1L was up-regulated in most cancers." (PMID 39095556, 2024). "Then, we evaluated the methylation level of SEH1L promoter between cancer and normal tissue." (PMID 39095556, 2024). "Nevertheless, the function of SEH1L in cancer is still in need of thorough research." (PMID 39095556, 2024). "Recently, multiple studies have suggested that SEH1L may serve as a potential biomarker in cancer." (PMID 40034747, 2025). "Recently, several studies reported that SEH1L may function as a biomarker in cancer." (PMID 39095556, 2024). "In this research, we performed a systematic bioinformatic analysis about SEH1L using TCGA, Timer 2.0, Cbioportal, UCLAN and CellMinerTM databases in pan-cancer." (PMID 39095556, 2024). "At first, we detected the expression of SEH1L in HCC cell lines and cancer tissues." (PMID 39095556, 2024).
infection (1 paper, 2015). The state of being infected such as from the introduction of a foreign agent such as serum, vaccine, antigenic substance or organism. "Research in humans and murine models using infection with S. aureus as phenotypic trait have suggested different positional candidate genes, e.g., SEH1L, TNFAIP8, KLK, and CDON." (PMID 26612358, 2015).
osteoarthropathy (1 paper, 2025). "Bioinformatics analyses have also identified SEH1L as a pivotal ubiquitin-related gene involved in immune infiltration in patients with osteoarthropathy." (PMID 40781725, 2025).
SEH1L also shares sentences with these, for which no sentence is quoted: Autoimmunity (1 paper); bladder cancer (1); colon adenocarcinoma (1); HIV-1 infection (1); knee osteoarthritis (1); lung squamous cell carcinoma (1); mesothelioma (1); neurodevelopmental disorder (1); ovarian carcinoma (1); pancreatic adenocarcinoma (1); peripheral neuropathy (1); prostate adenocarcinoma (1); stomach adenocarcinoma (1); uveal melanoma (1).